IL18 (interleukin 18)
Diseases named in the same sentence as IL18 in open-access papers (continued):
Sharing a sentence is not in itself a finding about the gene and the disease.
tumor (continued). "The results showed that the expression of CD2, SPN, IL18, PTPRC, GZMA, and TLR7 was upregulated in the tumor group compared with the normal group (p < 0.05)." (PMID 36591509, 2022). "Drakes and colleagues demonstrated that T-cell receptor (TCR)-modified T-cells with IL-18 expression created a superior proinflammatory TME, which improved overall survival of mice in the pmel-1 syngeneic tumor model." (PMID 35739593, 2022). "Due to the results obtained from videos 1 and 2, it seems that high infiltration into tumor islets along with low motility of TVM cells indicate that cell-cell interactions may be an important part of the antitumor mechanism after systemic IL-12+IL-18 expression." (PMID 36330506, 2022). "The present work demonstrated that the single administration of DCs transduced for the production of IL-12 and/or IL-18 increases the influx and activity of CD4+ and CD8+ T lymphocytes and decreases CD11b cells into the tumor microenvironment." (PMID 35372586, 2022). "The DAMPs, IL-1β and IL-18 released by pyroptosis of tumor cells can also effectively initiate CD8+ T cell expansion and promote NK cell recruitment, activate a tumor immune response, and improve the efficacy of immunotherapy." (PMID 36513682, 2022). "Depletion of IL-18 expression in macrophage showed similar effects with IL-18BP treatment on HOS and SJSA-1 tumor cells." (PMID 36274066, 2022). "Along with IL-18, IFN-γ contributes in priming of cytotoxic cells for killing tumor cells and in antiangiogenic mechanisms." (PMID 35264972, 2022). "Administration of DCs transduced for production of IL-12 alone and in combination with IL-18 increased the inflow and activity of CD4+ and CD8+ T lymphocytes in the tumor microenvironment and tumor-draining lymph nodes." (PMID 35372586, 2022). "While IL-18 also has a tumor-suppressive effect that it was shown to activate CD4+T cells and NK cells and suppress the progression of tumor metastasis." (PMID 36237303, 2022). "Tumor tissues showed obviously higher expression levels of NLRP1, IL18, TNF, and CASP4 than did the normal tissues." (PMID 35785176, 2022). "GMP-compliant manufactured IL-18 TRUCKs targeting GD2 showed a high cytotoxic capability and were able to eliminate tumor cells while forming clusters around target cells." (PMID 35401506, 2022). "IL-18 can increase the expression of thrombospondin 1 by activating the JNK pathway, which increases tumor angiogenesis." (PMID 36185234, 2022). "After the NLRP3 inflammasome is activated, it causes an inflammatory cascade reaction, leading to the release of pro-inflammatory factors such as IL-1β, IL-18, IL-22, TNF-α, and the activation of inflammation-tumor signaling pathways such as NF-κB." (PMID 35292015, 2022). "In a Lewis lung cancer mice model, IL-18 suppresses tumor growth by down-regulating VEGF-A and VEGF-C expression in tumor tissues." (PMID 35626056, 2022). "Another study confirmed that IL-18 promoted the secretion of TNF-α and IFN-γ, which synergistically enhanced the cytotoxic function of tumor-infiltrating lymphocytes with IL-12 in GC, and produced an anti-tumor effect." (PMID 36185234, 2022). "Thus, we postulate that the use of DCs able for simultaneous IL-12 and IL-18 production additionally stimulated with tumor antigens may generate a favorable impact on the activation of antitumor immune response, especially if these vaccine cells are administered repeatedly." (PMID 35372586, 2022). "In addition, the CD40/CD40L immune checkpoint pathway, which rescues tumour cells from apoptosis, prolongs survival and enhances the proliferation, activation, or maturation of APCs, including primarily macrophages and DCs, to produce IL-12 or IL-18 to stimulate NK cells." (PMID 36298556, 2022). "Consistent with our results in the database, GZMA, GZMB, IL18, and IRF1 were decreased in tumor tissues than normal tissues." (PMID 35464869, 2022).
tumor (continued). "For instance, mice receiving IL-18 before or after challenge with CL8-1, both regimens significantly suppressed tumor growth and reduced the number of mice with growth of tumor from 60% (3/5) to 20% (1/5)." (PMID 35865545, 2022). "Except for inducing cell death, some inflammatory factors that are produced by pyroptosis, such as IL-1β, IL18, and HMGB1, can activate the cancer-promoting signaling pathways including MAPK and VEGF pathways, which accelerates tumor growth." (PMID 35000541, 2022). "Significant increases in IFNG, IL‐18, IL‐1β, IL‐8, TNF‐α, TLR4, MyD88, and NF‐κB levels were found in the P. copri and tumour control groups." (PMID 35735103, 2022). "However, type I IFNs, IL-12, IL-15 and IL-18 are produced by activated antigen presenting cells and other cell types that are often present in the tumor microenvironment, thus suggesting that an innate immune response may be important in the host anti-tumor response." (PMID 36330506, 2022). "IL-1RA, IL-18, and MIP-1β, predictors of early tumor progression in univariable analysis, are cytokines produced by monocytes." (PMID 36091056, 2022). "Seven pyroptosis-related genes (ELANE, IL18, CHMP2B, CHMP4C, CASP9, CHMP6, and CHMP2A) were downregulated in tumor tissues, while 31 pyroptosis-related genes were upregulated in tumor tissues." (PMID 35432539, 2022). "We unveil an important link between IL‐18 and tumor‐derived enhanced YAP1, which leads to a gene expression profile toward tumor promotion profiling." (PMID 34196131, 2022). "The pro-inflammatory cytokines, such as IL-12, IL-18, and IL-15, have been used to arm CAR-T cells (the fourth-generation CAR-T cells) to enhance tumor-killing capacity." (PMID 35874698, 2022). "To consider the role of spatial concentrations and gradients of IL9 and IL18, we investigated the tumor-to-stroma and stroma-to-serum gradients of IL9 and IL18 in our patient cohort." (PMID 36131941, 2022). "Some examples are reported in several studies that have demonstrated the release of chemokines and cytokines such as CCL21; IL-2; IL-4; IL-18; IL-24; IFN-γ; and LIGHT, also known as a lymphotoxin analogue, into the tumor microenvironment." (PMID 36077761, 2022). "Circulating levels of IL-18 were elevated in patients with HCC compared to controls and they significantly correlated with the presence of venous invasion and advanced tumor stages." (PMID 36313762, 2022). "DCs producing IL-18 and/or IL-12 also induced activation of CD4+ and CD8+ T cells in lymph nodes and high infiltration of CD4+ and CD8+ T cells to the tumor tissue." (PMID 35372586, 2022). "Being an immunogenic form of cell death, pyroptosis produces proinflammatory cytokines such as IL-1β, IL18 to facilitate the infiltration of immune cells to the immunosuppressive TME, demonstrating it can be utilized in anti-tumor therapy." (PMID 35432318, 2022). "Mature cDCs and pDCs (monocyte-derived) can secrete cytokines (IL-1β, IL-12, IL-18, IFN-γ, and TNF-α) that activate Vγ9Vδ2+ T cells, enhancing their proliferation and cytotoxic function (IL-18-mediated cytotoxicity against tumor cells)." (PMID 35880177, 2022). "The NLRP3 inflammasome alters the tumor microenvironment via secretion of pro-inflammatory cytokines IL1B (neutral in both cohorts) and IL18 (neutral in mKRAS, conserved in WT, SR = -1.144)." (PMID 36092893, 2022). "In this context, DC chemotaxis to the TME is activated by the ATP released by tumor cell death recognized through purinergic receptors and NLRP3 resulting in IL-1β and IL-18 production." (PMID 36230990, 2022). "Intestinal epithelial cells (IEC) naturally produce IL-18 at a relatively constant level, which is considered a crucial factor in inhibiting CRC tumor development, tumor reduction and maintaining mucosal equilibrium." (PMID 35694291, 2022). "qRT-PCR suggested that GSK3B, IL18 and VEGFA RNA expression level in tumor cells was remarkably higher in contrast with that in normal cells, in line with findings based on GEPIA platform." (PMID 36743929, 2022).
tumor (continued). "As previously observed in mRNA expression level, CASP4, GPX4, IL18, NLRP1, and IRF1 were upregulated in tumor samples, whereas PLCG1 was downregulated." (PMID 35000541, 2022). "The incorporation of IL-18 into the CAR-T construct is supported by its role in the enhancement of CAR-T proliferation and anti-tumor activity." (PMID 36389658, 2022). "For instance, inflammatory cytokines such as IL-1β, IL-6, IL-17, IL-18, IL-23, and TNF-α can lead to tumor growth through activation of pathways such as NF-κB and STAT351–54." (PMID 36085201, 2022). "PD-1 was found expressed on NK cells present in the tumor-infiltrating immune cells in NPC; PD-1 expression on NK cells was notably induced by IL-18, which was significantly higher in NPC biopsy than in normal nasopharynx." (PMID 33671917, 2021). "Interestingly, the absence of caspase-1 activity in tumor cells was not only associated with decreased mRNA levels of caspase-1 and downstream cytokines IL-18 and IFNγ, but also with upstream inflammasome sensors or regulators, among which NLRC5 is of particular interest." (PMID 33430344, 2021). "However, IL-18 also has a dual role as the presence of high amounts of IL-18 in serum of patients with tumors of different etiology, including RCC, is associated with disease progression and aggressiveness, and correlates with advanced tumor stage, worsened outcome and shorter overall survival." (PMID 34616407, 2021). "Collectively, these data show that CTXpre/CD4post induces a milieu that continuously generates tumor-suppressive IL-18Rαhi CD8+ T cells, which exert strong effector function in response to TCR and IL-18 signaling." (PMID 34493727, 2021). "A minor subgroup of CRCs (30%) (aCasp1− in tumor cells), mainly MSS CRCs, secrete “basal” mature IL-18 levels close to those of normal colon explant cultures, released by a few activated aCasp1+ macrophages." (PMID 33430344, 2021). "Lung tumor regression correlates with an increased immune cell infiltration, more secretion of IL-18 within the TME and higher expression of PD-L1 by tumor cells." (PMID 33510147, 2021). "Mechanistically, activation of P2RX7 leads to increased production of IL-18 in a NLRP3-dependent manner, which in turn activates NK and CD4+ T cells to produce IFN-γ and consequently increases tumor immunogenicity." (PMID 33510147, 2021). "When a cancer cell is undergoing pyroptosis, a large amount of IL-18 is released out of the cell, reshaping the microenvironment and inducing immune response, which may also explain the reason why IL-18 mRNA expression in normal tissue is higher than in tumor tissue." (PMID 34840571, 2021). "IL-18 blockade in osteosarcoma cancer was shown to inhibit MDSC recruitment and suppress tumour growth." (PMID 33918087, 2021). "Avanzi and colleagues designed armored IL18-secreting CAR T cells, which increased IFN-γ secretion and tuned the tumor microenvironment toward an IFN-γ signature." (PMID 34809678, 2021). "stEMF further upregulated the pro-inflammatory cytokine interleukin 18 (IL18) alongside early growth response 1 (EGR1), an important transcription factor with multifaceted roles in tumor formation and proliferation as well as inflammation." (PMID 34574442, 2021). "In preclinical studies, the MHC-I deficient tumors responded better to treatment of cytokine such as IL-12 and IL-18, raising the question of whether the efficiency of cytokine therapy relies on NK cells, considering the well-known role of NK cells in targeting MHC-I deficient tumor." (PMID 33262461, 2021). "In vitro, PD-L1 expression was induced on NK cells from healthy donors (HD) upon direct tumor cell recognition through NKG2D and was further up-regulated by monocyte-derived IL-18." (PMID 34616407, 2021). "As for skin LC, a significant production of APRIL, IL-18 and CXCL13 was markedly increased in the presence of Tfh and B cells." (PMID 34324611, 2021).
tumor (continued). "IL-18 in combination with IL-12, through the activation of NK and cytotoxic T-cells, produced IFN-γ, which contributed to tumor immunity and had anti-tumor activity in different preclinical models." (PMID 34627252, 2021). "Various stimulatory conditions were used to assess NK cell responsiveness including stimulation with the tumor cell line K562, with anti-CD16 monoclonal antibodies, with a mix of IL-12 and IL-18 inflammatory cytokines, or with PMA and ionomycin." (PMID 34071607, 2021). "Some cytokines/chemokines such as TNF-α, IL-18, and RANTES have been reported to be directly involved in tumor growth via the stimulation of their receptors expressed on the tumor cells." (PMID 34436224, 2021). "The only positive score for the IL18-treated tumors was the ICAI Infiltration Score, which estimates degree of tumor infiltration by immune cells." (PMID 34209203, 2021). "In vitro data also show that IL-18 can favor the differentiation of human CD56dim CCR7+ CD25+ CD83+ helper NK cells, which control tumor dissemination and CD8+ T cell activation through the crosstalk with DCs in the lymph nodes." (PMID 33584718, 2020). "Following tumor excision, IHC analysis was used to determine tumoral expression of apoptosis- and pyroptosis-related biomarkers, including NLRP3, IL-18, IL-1β, and caspase-1." (PMID 32209729, 2020). "M1 macrophages are conventionally activated macrophages that secrete pro-inflammatory cytokines such as IL-1β, IL-6, IL-8, IL-18, TNF-α, and IFN-γ, and exert an anti-tumor effect." (PMID 32993787, 2020). "IL-18 activates NK and Th cells for IFN-γ production and enhances their anti-tumour activity in cooperation with IL-12." (PMID 32183246, 2020). "In the present study, we systematically analyzed the impact of IL-2, IL-12, and IL-18 in parallel with TCR stimulation on proliferation, cytokine production, and anti-tumor activity of γδ T cells." (PMID 31947966, 2020). "IL-18, an IFN-γ-inducing factor with antitumor activity in murine tumor models, has been reported to enhance the proliferation, cytotoxicity and IFN-γ secretion of both NK and T cells." (PMID 33173202, 2020). "Since IL-18 can induce T cells to secrete IFN-γ, the specificity of IFN-γ in tumours is still confusing." (PMID 32760201, 2020). "Additional studies indicated improved tumor control in leukemia and melanoma models using CD19-CAR T cells that constitutively express IL18." (PMID 32041222, 2020). "Although IL-18/p38 MAPK pathway downregulates claudin-12 and promotes tumor invasion in breast cancer, indicating its possible anti-tumor effect, the upregulation of claudin-12 in colorectal cancer needs to be further studied." (PMID 31316506, 2019). "As initially reported, IL-18 activates NK cells to produce IFN-γ and enhance cytotoxicity against tumor cells in synergy with IL-12." (PMID 30717382, 2019). "Here, infiltration of anti-tumor effector cells, CD8+ T cells, NK cells, and γδ T cells was markedly increased by IL18 expression." (PMID 31731729, 2019). "IL-18 served a suppressive role in HCC progression by enhancing the differentiation, activity and survival of tumor-infiltrating T cells." (PMID 31492049, 2019). "DC-derived cytokines including IL-18, IL-12, and IL-15 activate NK cells, whereas transforming growth factor (TGF)-β and IL-10 from regulatory T cells or tumor cells inhibit NK cells." (PMID 31731729, 2019). "In that line, IL-12 in combination with IL-18, strengthens NK cell cytotoxicity, and has also been shown to be an efficient treatment to restore NK cell activity in RMA-S tumor bearing mice." (PMID 31547251, 2019). "These mutant strains can induce tumor cells to secrete antitumor cytokines, such as IL-1β, IL-18, and TNF-α, thereby suppressing the proliferation of tumor models in mice." (PMID 31598148, 2019).
tumor (continued). "In conclusion, our data suggest that IL‐18 overexpression induces oral SCC cell invasion and metastasis by promoting the tumor cell epithelial–mesenchymal transition via the Wnt/β‐catenin signaling pathway." (PMID 30524946, 2018). "The presence of cytokines in the ACP tumours was also assessed by multiplex ELISA against IL1B, IL6, IL8 (CXCL8), IL10, IL18, TNF (TNFα) and IFNG (IFNγ), which revealed the expression of all of these but IFNG in protein lysates from eight human ACPs." (PMID 29541918, 2018). "Thus, also in the absence of pathogen-derived stimuli, the action of MMPs (or other still unknown mechanisms), may allow IL-18 shedding from TAM and the induction of CCR7 expression in CD56dim tumor-associated NK cells (TA-NK), thus promoting their migration to SLO and TLS." (PMID 30364222, 2018). "IL-18 induced the secretion of IFN-γ, IL-2, GM-CSF, TNF-α by the NK cells, and these secreted cytokines exert antitumor effects by directly killing tumor cells or regulating the immune function." (PMID 30002398, 2018). "We used multiplex ELISA to demonstrate the presence of IL1B, IL6, IL8, IL10, IL18, TNF and IFNG in the cystic fluid and whole ACP tumour protein lysates." (PMID 29541918, 2018). "The end targets of these pathways, including cytokines (IL1A/B, IL6, IL8, IL18) and genes related to cell proliferation (JUN, SRF), were upregulated, suggesting that the activation of these TLRs leads to tumor growth." (PMID 29912993, 2018). "The antitumor immunity was shown to be associated with increase of Th1/Th2 cytokine ratio and upregulation of IL-12, IL-18, IFN-γ, and GM-CSF within the tumor tissues." (PMID 29857493, 2018). "Up-regulation of IL-18 can activate NLRP3, promote proliferation, inhibit apoptosis, and inhibit the anti-tumor effect of dexamethasone." (PMID 29312552, 2017). "IL-12 treatment inhibits tumor metastasis in the NKG2D and perforin-dependent manner, while the antimetastatic effect of IL-18 in the same setting is FasL dependent." (PMID 28955340, 2017). "Among the various cytokines, the combination of CART cells and IL-15 or IL-21 administration mediated the best anti-tumor response, followed by IL-2 and IL-7, whereas IL-18 and only CART cells treated mice had the heaviest tumor burden." (PMID 27409425, 2016). "The therapeutic use of IL-18 and IL-21 must, however, be carefully and extensively examined and developed as translational research, because it is well known that the cytokines transduce signals related to cellular survival, proliferation, and differentiation and, therefore, may help tumor growth." (PMID 25686210, 2015). "In this study, we co-expressed GM-CSF and IL-18 in colon carcinoma cells (CT26) and examined the anti-tumor effects compared with GM-CSF alone." (PMID 26186692, 2015). "In the end of tumor protective assay, the tumor free survival rate of respective group also showed similar results, which is about 40% (CT26/GM-CSF/IL-18), 25% (CT26/GM-CSF), 15% (CT26), and less than 5% (CT26/IL-18 and PBS control)." (PMID 26186692, 2015). "On the other hand, combination gene therapy of the IL-18 and TK/GCV system resulted in the complete rejection of a large tumor mass." (PMID 25051201, 2014). "Tumor tissue was analyzed for relative mRNA expression of a panel of different cytokines (IL1 β, IL2, IL6, IL18, TNF-α and IFN-γ)." (PMID 24676901, 2014). "We confirmed the tumor-specific promoter activity of the hTERT promoter and the antitumor effect mediated by the compound expression of HSV-TK and IL-18." (PMID 25051201, 2014). "Thus, targeting IL-18 in patients with T-ALL needs to be carefully examined because it may also result in reduction of the immune response as previously suggested for other tumours." (PMID 24778454, 2014). "IL-18 was proposed to have a role in IFN-γ mediated activation of STAT1, which is known to have a role in tumor suppression." (PMID 24273542, 2013).